CD4 (CD4 molecule)
Diseases named in the same sentence as CD4 in open-access papers (continued):
Sharing a sentence is not in itself a finding about the gene and the disease.
HIV-1 infection (continued). "Subsequently, a significant decrease in all thymocyte subpopulations may result, thus contributing to the overall depletion of CD4+ T cells in HIV-1 infection." (PMID 21639903, 2011). "Moreover, HSV-2-infected moDCs significantly increase α4β7 expression on CD4+ T lymphocytes and HIV-1 infection in DC-T cell mixtures in a RA-dependent manner." (PMID 21738472, 2011). "The CD4-independent HIV-1 infection occurs through acidic endosomes." (PMID 21541353, 2011). "Therefore ps20 is a novel marker of CD4+ T-cells rendered vulnerable to HIV-1 infection by regulating the fundamental biologic process of intercellular conjugate formation and consequently of potential importance in HIV-1 pathogenesis." (PMID 21545747, 2011). "Number of individual siRNA able to rescue HIV-1 infection in HeLa-CD4 cells." (PMID 22082156, 2011). "Since telomere length is associated with proliferative capacity, those naïve CD4+ T-cells still present after the initial HIV-1 infection would be unlikely to generate, or support, robust CD8+ T- and B-cell responses to HIV-1 or opportunistic infections." (PMID 21298072, 2011). "The mechanism by which cathepsin B inhibits the CD4-independent infection is suggested as follows; higher cathepsin B protease activity in SAOS-2, HeLa, and TE671 cells causes degradation of the HIV-1 particles in acidic endosomes, attenuating the CD4-independent HIV-1 infection." (PMID 21541353, 2011). "As we showed previously, the induction of NKp44L surface expression on uninfected bystander cells by the 3S motif renders them highly sensitive to NK lysis, a phenomenon that may lead to the CD4 depletion observed during HIV-1 infection." (PMID 20617170, 2010). "Importantly, the expression of GPI-scFv (X5) on the surface of human CD4+ T cells confers long-term resistance to HIV-1 infection, HIV-1 envelope-mediated cell-cell fusion and the infection of HIV-1 captured and transferred by human DCs." (PMID 20923574, 2010). "Moreover, we monitored DCIR levels in the CD4+ T cell subpopulation following acute HIV-1 infection of unseparated peripheral blood mononuclear cells." (PMID 21085612, 2010). "CD4 cell depletion and the resulting immune dysfunction are hallmarks of HIV-1 infection." (PMID 20617170, 2010). "We also observed an inverse correlation between the proportion of monofunctional CD8+ T cells and CD4+ T cell counts, which suggests that immune dysfunction as seen in late chronic HIV-1 infection is characterized by increasing proportion of exhausted monofunctional cells." (PMID 20638093, 2010). "Plasmacytoid DCs respond to localized HIV-1 infection in the submucosa and initiate inflammatory responses and recruitment of immune cells, and in particular CD4 T cells, which may fuel the early expansion of HIV-1." (PMID 21994702, 2010). "The 2G12 dimer prevented CD4 T cell loss in the peripheral blood following HIV-1 infection, whereas the 2G12 monomer did not provide protection." (PMID 21187894, 2010). "Given the unique capability of mDCs to promote HIV-1 infection of CD4+ T cells in vitro, we hypothesize that in vivo, mDC trans-infection could augment viral dissemination in the lymphoid tissue and significantly contribute to HIV disease progression." (PMID 20360840, 2010). "Expansion of specific CD4+ cells in response to vaccination is important in that these cells play a key role in activation of both B cells and CD8+ cells, and in controlling CTL responses, and are linked to the control of HIV-1 infection and replication." (PMID 21087527, 2010). "As these cells are patrolling mucosal surfaces, a portal of entry for various pathogens including human immunodeficiency virus type-1 (HIV-1), we investigated the impact of TLR stimulation on productive HIV-1 infection of DCs and viral spreading to CD4+ T cells." (PMID 19419540, 2009).
HIV-1 infection (continued). "Initial HIV-1 infections of SCID-hu Thy/Liv animals resulted in a near-eradication of CD4+/CD8+ DP thymocytes and a decrease in the CD4+ SP T cell population of the human implanted tissue, a depletion shown to be reduced upon treatment with several anti-HIV compounds." (PMID 19674458, 2009). "CD4+ T lymphocytes are the natural target of HIV-1 infection." (PMID 19656383, 2009). "As previously reported, cell-free HIV-1 infection remains restricted in the BeWo-CD4+ cell line." (PMID 19445667, 2009). "In addition to CD4 T cells, cells from the monocyte/macrophage lineage are also major targets of HIV-1 infection." (PMID 19492063, 2009). "The objective of the work described in this report is to gain insight into the mechanism of restriction of cell-free HIV-1 infection in the BeWo trophoblast cell line by investigating viral entry in both wild-type and CD4+ cells as well as the potential role of proteasomal degradation." (PMID 19445667, 2009). "Notably, wt HIV-1 infection increased the number of 7AAD+/p24- cells (33.2% of all CD4+ T lymphocytes; 38.0% of all p24- CD4+ T lymphocytes; lower right quadrant), reflecting bystander killing in response to virus infection." (PMID 19146681, 2009). "To further analyze how Nef accelerates depletion of CD4+ T lymphocytes in HLAC HIV-1 infection, we sought to determine whether Nef primarily affects the killing of productively infected or uninfected (bystander) CD4+ T cells." (PMID 19146681, 2009). "Although the precise mechanisms involved in this blockage remain unidentified, a number of cellular factors have been reported as restriction factors to HIV-1 infection in quiescent CD4+ T-cells (reviewed in more detail), including Murr1 and most recently APOBEC3G." (PMID 19300495, 2009). "The dysregulation of the immune response appears early during HIV-1 infection when individuals gradually lose their T lymphocyte proliferative responses to recall antigens, alloantigens and mitogens, before the severe reduction in CD4 T-cell count appears." (PMID 19538732, 2009). "During primary HIV-1 infection, a high degree of viral replication and CD4+ T-cell depletion occur." (PMID 19412542, 2009). "Moreover, prostratin also inhibits de novo HIV-1 infection via posttranscriptional downregulation of the cellular HIV-1 receptors CD4 and CXCR4 (CXC chemokine receptor 4)." (PMID 19564922, 2009). "Instead, the formation of gp120/anti-CD4bs complexes during HIV-1 infection may actually contribute to further suppression of anti-viral CD4 T cell responses." (PMID 18638381, 2008). "A number of factors were predictive of infant mortality by univariate analysis including infant HIV-1 infection, low birth weight, maternal syphilis, anemia, low CD4 count, clinical stage of maternal disease and whether mother was living at 15 months." (PMID 19009021, 2008). "Such immune-based therapeutic strategies used in treated, chronic HIV-1 infection may enable the induction of virus-specific CD4+ T cells essential for the subsequent 'kick-start' and expansion of virus-specific CD8+ T cells." (PMID 18976455, 2008). "PBMCs include CD4+ T-cells, the natural targets of HIV-1 infection, which also express A3G." (PMID 19057663, 2008). "It would then be plausible that such mediators could impair HIV-1 infection of CD4+ T cells in DC-T cell cocultures through an anti-proliferative effect, leading to a decreased viral production." (PMID 18373845, 2008). "It is plausible that HIV-1 infection (and Tat expression) may promote cell cycle progression in dividing/activated CD4+ T cells." (PMID 18237430, 2008). "However, the ability of CD4+ T cells and macrophages to support a productive HIV-1 infection depends upon the physiological status of the cell." (PMID 18773076, 2008). "Besides, in early and later stages of HIV-1 infection, the virus was found to replicate predominantly in these CD4+ T cells." (PMID 19046417, 2008).
HIV-1 infection (continued). "In addition, the contribution of the CD8+CD4+ T-cells in the total CD8+ T-cell population during HIV-1 infection was less than 2%." (PMID 18923697, 2008). "It is also unclear whether resident macrophages and CD4+ T cells of the testis are a target for infection in the early stages of HIV-1 infection or whether this is a feature only of the late stages of the disease." (PMID 17266752, 2007). "Determining the host factors within TEMRA cells that restrict R5-tropic viruses and endow HIV-1–specific CD4+ T cells with this ability may result in novel therapeutic strategies against HIV-1 infection." (PMID 17465678, 2007). "If TEMRA cells contain a high proportion of HIV-specific effector T cells, this would overcome a potential Achilles' heel of the immune response during HIV-1 infection; that is, CD4+ T cells that are activated by HIV-1 antigens themselves become highly susceptible targets for the virus." (PMID 17465678, 2007). "We also demonstrated that these conserved regions prime CD8+ and CD4+ T cell to highly conserved epitopes in humans and that these epitopes, although usually subdominant, generate memory T cells in patients during natural HIV-1 infection." (PMID 17912361, 2007). "Furthermore, productive HIV-1 infection was established in vaginal CD4+ T cells, indicated by viral protein synthesis in individual T cells within 2–3 days." (PMID 17306567, 2007). "Conferring an HIV-resistant ability to HIV-1–specific CD4+ T cells could lead to novel strategies aimed at potentiating a protective immune response against HIV-1 infection." (PMID 17465678, 2007). "It is believed that HIV-1 infected CD4+ T cells, macrophages and spermatogenic cells from the testis and epididymis are shed into the semen during the course of HIV-1 infection, thus contributing to viral transmission, though further evidence to support this opinion is needed." (PMID 17266752, 2007). "Besides, it is possible that the 20–40% of memory CD4+ T cells that are left uninfected in the mucosal tissues of the average patient is enough to support a second HIV-1 infection, especially if new CD4+ T cells are recruited to these tissues." (PMID 17892568, 2007). "In addition to CD4+ T lymphocytes, dendritic cells and macrophages are considered reservoirs for HIV-1 infection, but information on the replicative state of the virus within these cells is limited." (PMID 16412247, 2006). "In addition, a number of cellular molecules that aid in HIV-1 infection such as cellular receptors and coreceptors CD4, CCR5 and CXCR4 have also been successfully tested in CD34 cell derived macrophages and T cells." (PMID 16623949, 2006). "Moreover, HIV-1 infection leads to CD4 T cell depletion in peripheral blood and thymus, thus mimicking key aspects of HIV-1 pathogenesis." (PMID 17078891, 2006). "The surface markers analyzed were CD14, a monocyte/macrophage specific marker, HLA-DR (a class II MHC molecule found on antigen presenting cells), CD4, the major receptor for HIV-1 infection, and CCR5 and CXCR4, chemokine receptors which are critical coreceptors essential for HIV-1 entry." (PMID 16623949, 2006). "In vitro analysis of susceptibility of donor CD4 T cells, and of the various transduced HeLa cell lines supported the absence of significant differential restriction of HIV-1 infection by the various huTRIM5α alleles." (PMID 16925802, 2006). "We found low levels of CD4 T cell activation and reduced PBMC susceptibility to HIV-1 infection in Central African EUs, indicating that both may contribute to the resistance to HIV-1 infection." (PMID 16792805, 2006). "Thus, in HIV-1 infection where there is a decrease in CD4+ cells and an increase in CD8+ cells, the reversal of the CD4/CD8 to <1.0 should in theory be useful for diagnosis of HIV-1 infection." (PMID 15683549, 2005).
HIV-1 infection (continued). "Increase in the intracellular perforin content seems to be the normal consequence of the process of post-thymic development, and it is also valid in the case of CD4+ T-cell differentiation, since cytotoxic CD4+ T-cells, whose proportions are increased during HIV-1 infection, are CD57+." (PMID 14966528, 2004). "Early treatment of acute HIV-1 infection led to normalization of CD4+ T cell counts in most patients (median, 753 cells/mm3; range, 492–986), but the effect of treatment interruption was variable, even in those doing well, as defined by sustained low viral loads." (PMID 15526059, 2004). "Blocking of CD4 binding sites on HIV-1 gp120 by monoclonal antibodies or a CD4-IgG2 recombinant protein has been shown to be sufficient to inhibit HIV-1 infection of human cervical tissue ex vivo and in preventing virus transmission to macaque monkeys when applied vaginally." (PMID 15485580, 2004). "Furthermore, bnAbs that efficiently suppress cell-free HIV-1 infection of CD4+ T cells or interfere with viral cell-to-cell transmission might be compromised in their ability to suppress CD4+ T cell-mediated enhancement of HIV-1 macrophage infection." (PMID 40130873, 2025). "However, the function of m6A modification in regulating HIV-1 infection of primary CD4+ T cells remains unclear." (PMID 41085277, 2025). "Thus, amyloid attachment factors lowering the threshold of CD4 and coreceptors required for efficient viral entry might be particularly important for facilitating HIV-1 infection and spread in the brain." (PMID 39827271, 2025). "Indeed, Itgα4β7 has been reported as a marker of CD4+ T-cells highly permissive to HIV-1 infection." (PMID 41227377, 2025). "Among 165 individuals with chronic HIV-1 infection, there exists an inverse association between microRNA-29a (miR-29a) levels and both HIV viral load as well as the extent of immunosuppression (as indicated by the CD4+ T cell count and the CD4+ T/CD8+ T ratio)." (PMID 40296890, 2025). "Furthermore, LY6E modulates HIV-1 infection in a CD4-dependent manner in target cells." (PMID 38169284, 2024). "Besides, it has been shown that high levels of CD4+α4β7+ T cells increased the susceptibility to HIV-1 infection in nonhuman primates and heterosexual women." (PMID 38980725, 2024). "Therefore, we next examined whether the mitochondrial fission and fusion balance was altered in naive CD4+T cells and, if so, how it contributed to the increased MM of CD4+T cells in HIV-1 infection." (PMID 38267841, 2024). "Also, it has been reported that MVC may induce beneficial immunological changes in HIV-1 infection, inducing a good recovery of immune cells such as CD4+ and/or CD8+ lymphocytes from people with HIV55,56." (PMID 38886484, 2024). "A CD4+ T cell count of 382 cells/UL raised the possibility of idiopathic low CD4+ T cell syndrome, defined as persistent CD4+ T cell lymphopenia in the absence of HIV-1 infection or any other cause of immunodeficiency." (PMID 39417495, 2024). "In addition, the number of activated CD4+ T cells at the site of inflammation may have also been increased, thereby providing additional target cells to facilitate HIV-1 infection." (PMID 38303112, 2024). "Thus, phenotypic changes in T helper subset composition are unlikely to explain increases in HIV-1 infection susceptibility in CD4+ T cells isolated from the EM." (PMID 39872519, 2024). "Unexpectedly, in the current study we found that these changes do not appear to be associated with direct changes in CD4+ T cell infection susceptibility, with CD4+ T cells of post-menopausal women remaining more susceptible to HIV-1 infection regardless of T helper subset assessed." (PMID 39872519, 2024). "Thus, despite the changes observed in the EM, menopause did not alter the HIV-1 infection susceptibility of CD4+ T cells isolated from the CX nor ECX as measured by relative and absolute infection frequency." (PMID 39872519, 2024).
HIV-1 infection (continued). "Moreover, it has been shown that HIV-1 infection of macrophages significantly stabilizes their interactions with CD4+ T cells compared to uninfected macrophages for more efficient virus cell-to-cell spreading and cis-infection of target CD4+ T cells." (PMID 38400063, 2024). "Finally, Stimulated emission depletion (STED) microscopy performed in primary human MoDC revealed DC-SIGN-dependent submembrane nanoclusters formed with ATG9, which was required to degrade incoming viruses and further limit DC-mediated transmission of HIV-1 infection to CD4+ T lymphocytes." (PMID 37240354, 2023). "Therefore, the level of expression of the gelsolin enzyme could restrict HIV-1 infection of CD4+ lymphocytes at a prefusion step." (PMID 37685911, 2023). "Having demonstrated that GPI-scFv X5 in transduced CD4+ CEMss cell lines effectively blocked HIV-1 infection in trans from iDC or mDC, we next evaluated whether GPI-scFv X5 transduced human primary CD4+ T cells would be protected from DC-mediated HIV-1 infection." (PMID 37781368, 2023). "We showed in the current work, that targeting inflammasome activation early after HIV-1 infection using the caspase-1 inhibitor VX-765 might represent a potential therapeutic strategy to improve CD4+ T cell homeostasis, and to reduce viral load and immune activation." (PMID 36800238, 2023). "Importantly, IFI16 restricts HIV-1 infection in macrophages but promotes HIV-1 induced CD4+ T cells death by pyroptosis and thus may drive HIV-1 pathogenesis." (PMID 36800238, 2023). "It is also possible that IL-1β release after HIV-1-dependent CARD8 activation after HIV-1 infection could contribute to pathogenesis since IL-1β induces the differentiation of Th17 cells, a highly HIV-susceptible CD4+ T cell subtype, as well as the recruitment of other target immune cells." (PMID 37417868, 2023). "Additionally, PVR/CD155 appears to play a role in NK cell immunity in HIV-1 infection, in which downregulation of the receptor on infected CD4+ target T cells, a process mediated by the viral Nef protein, leads to increased antiviral activity among KIR2DL5-positive NK cells." (PMID 38149259, 2023). "HIV-1 Infection of macrophages by heterotypic cell fusion requires interaction between the surface viral envelope glycoprotein gp120 expressed on infected T cells and CD4/CCR5 on the macrophage targets, as it was totally abrogated by anti-CD4 and anti-gp120 antibodies, T20, or Maraviroc." (PMID 36988579, 2023). "Since the primary target of HIV-1 infection, CD4 + T cells, are often found on activated endothelial tissues which display P-selectin in inflammatory conditions, we were interested in testing whether virions captured by P-selectin could be transferred to nearby permissive cells to elicit infection." (PMID 35597982, 2022). "We next characterized whether GPI-10E8 could protect human CD4+ T cells from HIV-1 infection." (PMID 34821542, 2022). "In a humanized mouse model, GPI-X5-transduced primary CD4+ T cells were selected in the peripheral blood and lymphoid tissues upon HIV-1 infection and after being cotransfused with HIV-infected cells, the transduced CD4+ T cells could significantly reduce viral loads and viral RNA copy numbers." (PMID 34821542, 2022). "Myeloid-derived dendritic cells, including Langerhans cells, stimulate naïve CD4 T cells to mature into Th1 cells which express high levels of the receptor CCR5, potentially rendering them more susceptible to HIV-1 infection due to the HIV-1 co-receptor expression." (PMID 36325020, 2022). "Consequently, CD4+ T lymphocytes are the main target cells of HIV-1 infection." (PMID 35205318, 2022).